PCSK9 (proprotein convertase subtilisin/kexin type 9)
Diseases named in the same sentence as PCSK9 in open-access papers (continued):
Sharing a sentence is not in itself a finding about the gene and the disease.
dyslipidemia (continued). "This trend was further confirmed in another randomized trial, on metabolic syndrome patients, in whom the dietary intervention with lupin proteins led to an 8% drop in LDL-cholesterol, with a decrease of 12.7% (vs. baseline) of PCSK9 levels." (PMID 32429343, 2020). "Moreover, in a recently published paper regarding our investigation, we confirmed that PCSK9 seems to be a novel marker of psoriasis and a putative explanation of lipid disturbances, which are common in patients with psoriasis and are vital for the further developing of metabolic syndrome." (PMID 32456228, 2020). "Some reports have also correlated resistin with hypertension, with a mechanism that is not fully understood, with atherogenic dyslipidemia, by modulating SREBP1-SREBP2 pathways, and with proprotein convertase subtilisin/kexin type 9 (PCSK9)." (PMID 31694146, 2019). "Consistent with PCSK9, the significant effect of ANGPTL3 on plasma lipid levels has raised interest in ANGPTL3 as a therapeutic target for the treatment of dyslipidemia and CVD." (PMID 29334984, 2018). "In conclusion, siRNA-mediated inhibition of SCAP resulted in a significant reduction in circulating PCSK9 and LDL-C in rodent and primate models supporting SCAP as a novel target for the treatment of dyslipidemia." (PMID 27707816, 2016). "Statins, as the cornerstone of dyslipidemia management, reduce circulating and intracellular cholesterol levels, but this reduction also leads to the upregulation of sterol regulatory element-binding protein 2 (SREBP-2) and PCSK9." (PMID 40089775, 2025). "We present a series of cases from our department in which patients with IMNM were treated with PCSK9 inhibitors for dyslipidemia after their symptoms improved, with no relapse of myositis." (PMID 40249406, 2025). "Furthermore, plasma proprotein convertase subtilisin/kexin type 9 (PCSK9), which also participates in dyslipidemia in obesity, were comparable between Apoo+/+ and Apoo−/− mice." (PMID 38830896, 2024). "This unique mechanism makes PCSK9 inhibitors a valuable addition to the treatment arsenal for managing dyslipidemia, especially in patients who have not reached target LDL-C levels with standard therapies." (PMID 39650150, 2024). "Proprotein convertase subtilisin/kexin type 9 (PCSK9) inhibitors have emerged as a potent therapeutic option for managing dyslipidemia, particularly in patients who do not achieve target lipid levels with statins alone." (PMID 39457689, 2024). "In addition to PCSK9, targeting ANGPTL3 can be considered as avaluable therapeutic approach for dyslipidemia management." (PMID 39228490, 2024). "Correlation between the PCSK9 serum level and TChol as well as LDL concentration may help to understand drug induced dyslipidemia after cyclosporine." (PMID 37763277, 2023). "In patients with type 2 diabetes and hypercholesterolemia or mixed dyslipidemia treated with statins, PCSK9 inhibitors significantly reduced LDL-C, non-HDL-C and apoB levels." (PMID 36936164, 2023). "Therefore, commercially available PCSK9 inhibitors can lower circulating LDL-C, thereby treating dyslipidemia in T2DM." (PMID 36936164, 2023). "There are numerous novel molecules that have been introduced in the treatment of diabetes mellitus, dyslipidemia, and cardiovascular disease, including glucagon-like peptide 1 (GLP-1) agonist, and proprotein convertase subtilisin-kexin type 9 (PCSK9) inhibitors." (PMID 38202174, 2023).
dyslipidemia (continued). "A proportion of patients with dyslipidemia, such as those with familial hypercholesterolemia, are not responsive to drugs commonly used to treat dyslipidemia, such as high-dose statins, ezetimibe, or PCSK9 inhibitors." (PMID 37914738, 2023). "Furthermore, it is noteworthy that PCSK9 has an adverse effect on NAFLD development and is correlated with cardiometabolic factors or metabolic syndrome." (PMID 34996457, 2022). "In animal model experiments conducted on 30 male rabbits with dyslipidemia, treated with 10-Dehydrogingerdione, a novel cholesteryl ester transfer protein (CETP) inhibitor, which is able to suppress PCSK9 expression, induced a marked decrease in the soluble sCD40L and sP-selectin." (PMID 35326219, 2022). "To date, there is little evidence in transplant recipients, but PCSK9 inhibitors have been shown to be a very effective treatment for dyslipidemia, with a reported reduction in LDL values of up to 50%." (PMID 35887846, 2022). "Further research is needed to better define the role of non-statin therapies, including ezetimibe, PCSK9 inhibitors, bempedoic acid and icosapent ethyl, in the management of dyslipidemia in cancer patients." (PMID 35548413, 2022). "After six months of add-on PCSK9-i therapy, only 42.9% of FH subjects attained LDL-C targets according to the European Society of Cardiology/European Atherosclerosis Society guidelines 2019 for the management of dyslipidemias." (PMID 33745063, 2021). "As per the Institute for Health and Care Excellence (NICE) guidelines, PCSK9 inhibitors alirocumab and evolocumab are recommended for patients with primary hypercholesterolemia or mixed dyslipidemia that is not controlled with statins." (PMID 34829831, 2021). "At present, interest is also focused on proprotein convertase subtilisin/kexin type 9 (PCSK9) inhibitors, which are medications able to regulate both lipoprotein (a) and dyslipidemia, and may have a potential in controlling the progression of AS." (PMID 32664529, 2020). "Therefore, medications designed to reduce their levels, such as statins or proprotein convertase subtilisin/kexin type 9 (PCSK-9) inhibitors, may be beneficial not only in dyslipidemia treatment but also in the prevention of tauopathies." (PMID 39202319, 2024). "Moreover, we did not provide any information on novel therapeutics, such as proprotein convertase subtilisin/kexin type 9 inhibitors or bempedoic acid, which are paving the way to a novel chapter in the treatment of dyslipidemia." (PMID 39361921, 2024). "Therefore, the present study hypothesized that anti-PCSK9 mAb1 may reduce the HFD and zymosan-induced dyslipidemia and arterial inflammation." (PMID 35911646, 2022). "However, studies to date have not shown an association between PCSK9 inhibitors and low HDL-C or increased risk of diabetes, metabolic syndrome, or obesity." (PMID 32035487, 2020). "It was, therefore, the purpose of the present study to investigate the interactions of PCSK9, apoC3, and sdLDL-C with current dyslipidemias, and identify their levels in predicting dyslipidemias in a large cohort of Chinese non-treated patients undergoing coronary angiography (CAG)." (PMID 27713142, 2017). "This preparation may potentially be a useful therapy to normalize dyslipidemia without significant side-effects, either alone as a single-agent treatment or in combination with other therapies like statins or PCSK9 inhibitors." (PMID 28095913, 2017).
dyslipidemia (continued). "Although prior studies have explored possible correlations of PCSK9, apoC3, and sdLDL-C with lipid profile, including TG, LDL-C, and HDL-C, and their role in atherogenisis, few of them assessed the role of these parameters in determining current dyslipidemias and compared the discordance." (PMID 27713142, 2017). "In a cohort of patients with dyslipidemia at very high cardiovascular risk, we investigated differences in LDL-C lipid target achievement, clinical outcomes, and persistence rates between users and non-users of PCSK9 monoclonal antibodies (PCSK9-mAb) over a 3-year observation period." (PMID 40760109, 2026).
coronary artery disease (246 papers, 2007 to 2026). "PCSK9 inhibitors have been widely used inclinical practice to reduce LDL‐C levels in high‐risk patients with coronary heart disease." (PMID 41573336, 2026). "RCTs have effectively evaluated the impact of HMGCR and PCSK9 inhibitors on coronary artery disease risk." (PMID 40764749, 2025). "Clinical trials have established an association between PCSK9 and immunological response, notably in patients with disorders associated with vascular aging, such as atherosclerotic disease and coronary artery disease." (PMID 40354375, 2025). "Coronary heart disease (CHD) served as a positive control to validate the causal relationship between PCSK9 inhibitors and various cancers." (PMID 38275613, 2024). "Studies have shown that PCSK9‐mediated increases in LDL‐C are strongly associated with the progression of cardiovascular diseases such as coronary heart disease." (PMID 38344397, 2024). "For instance, the identification of the PCSK9 gene’s association with coronary artery disease risk has led to the development and successful application of PCSK9 inhibitors." (PMID 38660492, 2024). "Effects of HMGCR were compared with proprotein convertase subtilisin kexin 9 (PCSK9) inhibitors, common lipid-lowering drugs, using coronary heart disease risk as a positive control." (PMID 39034950, 2024). "PCSK9 concentration, which was associated with both lipoprotein values and inflammatory parameters, was associated with the extent of coronary disease in the CAD patients." (PMID 36768292, 2023). "For example, naturally occurring PCSK9 mutations which lower LDL-C by as little as 0.5 mmol/L (20 mg/dL) reduce the lifetime risk of incident coronary heart disease by 50%13." (PMID 37770440, 2023). "There is growing evidence that PCSK9 gene mutations are directly interrelated with body mass index (BMI), hypercholesterolemia and coronary artery disease (CAD)." (PMID 36980866, 2023). "In young males with myocardial infarction, higher level PCSK9 exacerbates the severity of coronary artery diseases and increases the risk of MACEs." (PMID 36970356, 2023). "A 15-year prospective study demonstrated that nonsense heterozygous mutations in PCSK9 not only reduced LDL-C levels by 28% but also decreased the incidence of coronary heart disease by 88%." (PMID 38027179, 2023). "An increasing number of high-risk patients with coronary heart disease (similar to acute myocardial infarction (AMI)) are using PCSK9 inhibitors." (PMID 35832650, 2022). "In patients with stable coronary artery disease, PCSK9 was associated with monocyte subsets, especially with intermediate monocytes, which are characterized by CD14++CD16+ on their surface and express strong pro-inflammatory behaviors." (PMID 35806908, 2022). "Previous studies showed that the concentration of circulating PCSK9 was independently associated with fibrinogen, the main protein associated with circulating blood coagulation, in patients with stable coronary artery disease (CAD)." (PMID 35566668, 2022). "The gain of function mutations of the coding gene for PCSK9 have been associated with hypercholesterolemia, and, therefore, with a higher risk of coronary artery disease." (PMID 35323669, 2022). "In the same line, fibrinogen levels have been associated with PCSK9 levels in patients with stable coronary disease independently of traditional cardiovascular risk confounding." (PMID 34336112, 2021). "The proprotein convertase subtilisin kexin/type 9 (PCSK9) gene mutations was first identified to cause autosomal dominant hypercholesterolemia for a risk factor of coronary heart disease." (PMID 34504788, 2021). "The PCSK-9 gene also contains one of 27 loci associated with an increased risk of coronary artery disease." (PMID 33808697, 2021). "Mendelian randomization analysis using our sample lacked the necessary statistical power to derive robust conclusions regarding the causality of trans PCSK9 variants and coronary artery disease or even LDL-C levels." (PMID 34659352, 2021).
coronary artery disease (continued). "The data of the present study will help to further optimize risk stratification of coronary heart disease and provide more scientific and reasonable evidence for clinical application of Pcsk9 inhibitors, especially among young people." (PMID 34044829, 2021). "A positive association between circulating PCSK9 and TF in patients with stable coronary artery disease points in the same direction." (PMID 34884442, 2021). "Dual lipid-lowering therapy with ezetimibe or inhibitors of proprotein convertase subtilisin kexin type 9 (PCSK9) has been shown to be more effective than statin monotherapy in high-risk patients with coronary artery disease." (PMID 32460779, 2020). "Several of the variants trended towards association with ischemic heart disease, with the strongest association seen for rs639750 in PCSK9 (p = 0.0065, OR 0.96)." (PMID 30774981, 2019). "Nonsense mutations in PCSK9 are associated with an 88% reduction in the risk of coronary heart disease (CHD)." (PMID 31345219, 2019). "Gain-of-function mutations in PCSK9 can cause hypercholesterolemia leading to premature coronary heart disease, whereas loss-of-function mutations are associated with reduced plasma levels of LDL-C and the risk of coronary heart disease." (PMID 29343301, 2018). "A common genetic variant (rs11206510) ∼10 kb upstream of PCSK9 was also subsequently found to associate with coronary heart disease." (PMID 29270124, 2017). "Estimates and 95% confidence intervals (CI) of causal effect of low‐density lipoprotein‐cholesterol on coronary heart disease risk using genetic variants from PCSK9 gene region from various analysis methods." (PMID 26661904, 2016). "The study was to examine the association of plasma PCSK9 with lipoprotein subfractions in patients with stable coronary artery disease (CAD)." (PMID 25496400, 2014). "PCSK9 loss-of-function mutations result in low levels of low density lipoprotein cholesterol and protect against coronary heart disease while gain-of-function mutations have the opposite effect." (PMID 22794791, 2012). "PCSK9 variants that result in 'gain of function' have been linked to autosomal dominant hypercholesterolemia, while significant protection from coronary artery disease has been documented in individuals who carry 'loss of function' PCSK9 variants." (PMID 18547436, 2008). "In addition, a recent cross-sectional analysis also indicated that Hcy accelerates lipid accumulation through upregulation of PCSK9, resulting in a significant positive correlation between Hcy levels and risk of severe coronary artery disease." (PMID 40463467, 2025). "Variants in the PCSK9 gene were linked to coronary artery disease and cholesterol levels by GWAS." (PMID 40002898, 2025). "Another study reported that the ABO group might be a significant determinant of plasma PCSK9 level and coronary artery disease (CAD) susceptibility." (PMID 38972879, 2024). "In addition to its role in the degradation of LDL receptors, PCSK9 is associated with an increased risk of coronary artery disease." (PMID 38445291, 2024). "Researchers found that the inhibition of PCSK9 could reduce the risk of coronary heart disease by up to 88%, so they started prescribing patients a small interfering RNA called Inclisiran." (PMID 36768184, 2023). "Pharmacological inhibitors of PCSK9 lowering LDL-C levels and, thus, reducing the risk of coronary heart disease, were developed after the identification of healthy PCSK9 carriers, a process that could have been initiated by our analysis." (PMID 36777185, 2023). "Additionally, loss-of-function PCSK9 variants have been associated with a decrease in risk of coronary heart disease as well as extracoronary atherosclerotic phenotypes." (PMID 37762360, 2023).